GATA3 (GATA binding protein 3)
Diseases named in the same sentence as GATA3 in open-access papers (continued):
Sharing a sentence is not in itself a finding about the gene and the disease.
urothelial carcinoma (continued). "Our diagnosis also excluded sarcomatoid transformation of renal cell carcinoma and urothelial carcinoma through CA9, Pax-8, GATA3, P63, and P40." (PMID 40978053, 2025). "Immunohistochemical staining showed a similar profile of urothelial lineage with frequent positive expression of uroplakin II, GATA3, CK20, CK7, and S100P in both giant cell and conventional urothelial carcinomas." (PMID 39023556, 2024). "Standard discriminant analysis of this study demonstrated that, in descending order of importance for the urothelial lineage markers, UKP2, S100P, GATA3 and THBD were the most important predictors for urothelial carcinoma by gene expression." (PMID 33762601, 2021). "Immunohistochemistry was performed for uroplakin II, GATA3, CK7, CK20, and other representative markers positive for urothelial carcinoma." (PMID 27642214, 2016). "Poorly differentiated urothelial carcinoma sometimes shows similar morphology to IPLC with the following immunophenotype: CK7+, CK20−, GATA3+, and uroplakin II+." (PMID 27642214, 2016). "GATA3, a transcription factor belonging to the GATA family, proved to be a useful immunohistochemical marker for several malignancies, mainly breast and urothelial carcinomas." (PMID 25400965, 2014). "The negative staining of PSA ruled out prostate carcinoma, as well as urinary tract carcinoma by the negative staining of GATA3." (PMID 41515615, 2026). "It is noteworthy that these markers are not entirely breast-specific, as GATA3 can be expressed in certain renal neoplasms, neuroendocrine neoplasms, and urothelial carcinomas." (PMID 38902365, 2025). "Negative for urothelial carcinoma, the original bladder biopsy was reexamined: staining GATA binding protein 3 (GATA-3) negative, PAX-8 positive, more consistent with endometrial origin." (PMID 40678160, 2025). "GATA3 copy number changes are not critical drivers for deregulated GATA3 expression in urothelial carcinomas." (PMID 39979991, 2025). "However, GATA3’s expression in MBC (luminal subtypes) and urothelial carcinoma mandates cautious interpretation to avoid misclassifying PCMC as metastatic disease." (PMID 40969274, 2025). "In invasive urothelial carcinomas, a notable difference in GATA3 expression between the subgroups with non-muscular invasion and those with muscular invasion has been recorded." (PMID 39768217, 2024). "Upk1a/Upk1b staining was observed in 32% of GATA3 negative pT2-4 cancers and GATA3 staining was seen in 43% of Upk1a/Upk1b negative pT2-4 urothelial carcinomas." (PMID 37777995, 2024). "In this case, GATA3(+) staining of the metastasis to the supraclavicular lymph node revealed that the primary cancer was not squamous cell carcinoma of the tongue but urothelial carcinoma in the bladder." (PMID 35078521, 2022). "However, the poorly cohesive gastric carcinomas can express ER and urothelial carcinoma can be diffusely positive for GCDFP-15 and express nuclear GATA3." (PMID 31205468, 2019). "Since both primary EMPDs and urothelial carcinomas are positive for GATA3, GAT3 is not useful in distinguishing primary EMPDs from secondary EMPD caused by urothelial carcinoma and other markers should be sought for this purpose." (PMID 28693610, 2017). "While 96–100% of ovarian adenocarcinomas are CK 7+/CK 20−, compared with only 11–63% of bladder cancers, urothelial carcinomas display immunohistochemical GATA3 positivity whereas ovarian cells do not." (PMID 26634162, 2015). "FISH has so far not been utilized for GATA3 amplification analysis in urothelial carcinomas." (PMID 39979991, 2025).
urothelial carcinoma (continued). "In rare cases, urothelial carcinoma with glandular differentiation or metastatic colorectal adenocarcinoma may exhibit overlapping immunophenotypes; however, the absence of GATA3 and CDX2 in this case helped exclude those possibilities." (PMID 40662003, 2025). "Furthermore, GATA3, p63, S100P, CK20, and uroplakin II are markers of urothelial carcinoma." (PMID 39310501, 2024). "Urothelial carcinoma may mimic the solid pattern of IC, which is negative for GATA-3 and positive for PSA (as in our case)." (PMID 37374005, 2023). "In addition, GATA3 is not a breast-specific marker that can label other common sources of tumors, including urothelial carcinomas, squamous cell carcinomas, lung adenocarcinoma, pancreatic adenocarcinomas, endocrine tumors, soft tissue sarcomas, and others." (PMID 36284362, 2022). "Urothelial carcinoma could express both GATA3 and ER, but not GDFP-15 and mammoglobin, so the standard panel for differential diagnosis includes all of them, associated with PgR." (PMID 36248976, 2022). "GATA3 immunoreactivity was seen in most urothelial carcinomas but not in colorectal carcinomas." (PMID 28693610, 2017). "It has been noted that antibodies such as GATA3, CK7, 34βE12, and p63 are serving as potential markers for urothelial carcinoma, but these markers are not entirely specific and often require a combination to reach a definitive diagnosis." (PMID 40917856, 2025). "GATA3 is a zinc finger transcription factor with a higher sensitivity for triple-negative cancer than GCDFP-15, but it is expressed in urothelial carcinoma as well." (PMID 34410532, 2021). "Unlike GATA3, TRPS1 is not expressed in urothelial carcinoma." (PMID 40025593, 2025). "UC1/p-UC1 and UC2/p-UC2 expressed only luminal markers (KRT7, GATA3), supporting their classification as luminal-type urothelial carcinomas, while UC3/p-UC3 expressed basal markers (KRT5, KRT6) and KRT7 but lacked GATA3 and keratinization markers, confirming its basaloid subtype." (PMID 41387887, 2025). "In addition, the absence of elevated markers of urothelial carcinoma such as NECTIN4 and GATA3 in the present case suggests that the malignancy is unlikely to be derived from bladder cancer." (PMID 37240308, 2023).
bladder cancer (66 papers, 2012 to 2025). "Loss of GATA3 in a subset of bladder cancer, especially in high-grade tumors, was correlated with higher AR activity in males." (PMID 41228208, 2025). "A high level of GATA3 expression had earlier been suggested as a hallmark of the luminal subtype, which was linked to favourable disease outcomes in RNA‐based bladder cancer classifiers." (PMID 39539567, 2024). "In contrast to our results, high GATA3 expression is associated with low scores of infiltrating lymphocytes in the tumor microenvironment (TME) of bladder cancer." (PMID 38668712, 2024). "Although GATA3 can be used as a diagnostic marker for bladder cancer, many studies demonstrated that GATA3 inhibited cancer cell migration, invasion, and EMT." (PMID 35647011, 2022). "While GATA3 serves as a diagnostic marker for urothelial cancers, forced expression of GATA3 diminishes malignant propensity of bladder cancer cells." (PMID 33803938, 2021). "For example, GATA3 expression correlated with a loss of ERβ as well as with AR/ERα overexpression in bladder cancer." (PMID 28005163, 2017). "Although we were unable to associate the expression of GATA-3 to Th2 or another type of cell, it remains possible that this transcription factor serves as a good prognosis biomarker in bladder cancer, since its expression is associated with patient survival." (PMID 27237631, 2016). "In contrast, reductions in Bcl-6 and GATA-3 expression correlated with invasive and high-grade of bladder cancer and were associated with a decrease in disease-free survival." (PMID 27237631, 2016). "Loss of GATA3 expression in a subset of bladder cancers, especially high-grade and/or muscle-invasive tumors, as well as its correlation with the induction of tumor cell migration and invasion in vitro, suggests the role of GATA3 as a tumor suppressor." (PMID 28241422, 2017). "Of particular interest regarding sex differences is the GATA3 gene, a suggested prognostic biomarker for bladder cancer." (PMID 41228208, 2025). "Conversely, upregulation of GATA3 refers to a luminal subtype of bladder cancer, exhibiting better response to targeted treatments, including a knockout of GATA3, β-catenin, and PPAR-γ pathways, as well as anti-angiogenic therapy." (PMID 39768217, 2024). "Malignant arsenite-transformed UROtsa cells mimic basal muscle-invasive bladder cancer and are characterized by low expression of luminal markers (GATA3, FOXA1)." (PMID 38539513, 2024). "High expression of GATA3 correlates with luminal subtype and can predict survival and therapy response in bladder cancer." (PMID 38539513, 2024). "A loss of GATA3 function was consistently seen in high-grade invasive bladder cancer, suggesting the utility of GATA3 as a prognostic biomarker in addition to its utility in diagnostic procedures." (PMID 39768217, 2024). "GATA3 is another luminal marker that is expressed at low levels in basal muscle-invasive bladder cancer and in malignant UROtsa cells." (PMID 38539513, 2024). "A clinical study identified KRT5, KRT6, and GATA3 expression as the most effective classifier in predicting luminal versus basal subtypes of bladder cancer with an accuracy of 89%." (PMID 38539513, 2024). "In general, a depleted level of GATA3 suggests a basal subtype of bladder cancer that is more sensitive to immune checkpoint blockade therapy (ICB) and neoadjuvant treatments." (PMID 39768217, 2024). "This strategy identified a large module of Luminal TFs, including known Luminal-associated TFs (e.g., FOXA1/GATA3/PPARG), as well as TFs with yet unexplored roles in Luminal bladder cancer biology (e.g., HES1, FOXQ1, ZBTB7C, MECOM, GRHL2/3, and TBX3)." (PMID 36944729, 2023). "Rather, lineage plasticity in bladder cancers with squamous differentiation is associated with loss of expression of FOXA1, GATA3, and PPARG, transcription factors critical for maintenance of urothelial cell identity." (PMID 36323682, 2022).
bladder cancer (continued). "Experimental evidence suggests that the altered expression of certain transcription factors, such as Foxa1, Gata3, and Pparg, can affect the molecular subtypes of bladder cancer." (PMID 36077697, 2022). "Both FOXA1 and GATA3 also play a role in the differentiation of urothelial cells in human bladder cancers, and the expression of PPARγ, FOXA1 and GATA3 is negatively correlated to the grade of the tumor." (PMID 36293167, 2022). "We found that lineage plasticity in bladder cancers with SqD was associated with loss of expression of the FOXA1, GATA3, and PPARG transcription factors." (PMID 36323682, 2022). "Our previous study also revealed that ST3GAL6 can be repressed by a luminal-specific transcription factor, GATA3, in bladder cancer cells." (PMID 36092699, 2022). "GATA-3 and Caveolin-1 have been demonstrated as potential biomarkers of the biological behavior of canine bladder carcinoma, correlating with MC." (PMID 36299636, 2022). "A simple experiment demonstrated that forced expression of GATA3 diminished the proliferation of a bladder cancer cell line, suggesting that GATA3 has tumor suppressor activity in the bladder cancer cells." (PMID 33803938, 2021). "Our findings are largely in agreement with previously known work on the role of FOXA1 and GATA3 in the regulation and maintenance of oncogenic programs in luminal bladder cancers." (PMID 33858483, 2021). "Here, we extend these findings and show that GATA3 expression remained high in BCG-resistant bladder cancer tissue (MIBC and CIS lesions)." (PMID 33672843, 2021). "We have previously reported that expression of the transcription factor GATA3 is high in bladder cancer tissue prior to the onset of BCG therapy." (PMID 33672843, 2021). "A comprehensive literature search in PubMed database was performed for all immunohistochemical studies of ERα, ERβ and/or GATA3 in bladder cancer patients." (PMID 34690921, 2021). "We determine the genome-wide transcriptome, enhancer landscape, and transcription factor binding profiles of FOXA1 and GATA3 in luminal and basal subtypes of bladder cancer." (PMID 33858483, 2021). "The transcription factors PPARγ, FOXA1, and GATA3 play a role in the establishment of the luminal subtype of bladder cancer." (PMID 32822399, 2020). "Low GATA3 levels have been reported to regulate self-renewal and tumorigenicity in bladder cancer stem cells by modulating STAT3 expression." (PMID 33408272, 2020). "Focusing on tumor cells, GATA3 has been shown to prevent bladder cancer progression and metastasis by inhibiting cell migration and invasion as well as epithelial-to-mesenchymal transition in vitro." (PMID 28005163, 2017). "Expression of T-bet, GATA-3 and Bcl-6 genes was assessed using RT-qPCR in 65 bladder cancers from patients: 32 being diagnosed as low- and medium-grade, 31 as high-grade, 25 as muscle invasive stage and 39 as non-muscle invasive stage." (PMID 27237631, 2016). "The aim of this study was to investigate the clinical significance of three immune cell-related transcription factors, T-bet, GATA-3 and Bcl-6 in bladder cancer in Tunisian patients." (PMID 27237631, 2016). "Next, we analyzed T-bet, GATA-3, and Bcl-6 levels in relation to OS of patients with bladder cancer." (PMID 27237631, 2016). "The aim of this study is to assess the prognostic value of three genes in tumors from bladder cancer patients in Tunisia: T-bet, GATA-3 and Bcl-6." (PMID 27237631, 2016). "In summary, our analysis identified a set of human cell lines suitable for the study of molecular subtypes in bladder cancer, and furthermore indicates a cooperative regulatory network consisting of GATA3, FOXA1, and PPARɣ drive luminal cell fate." (PMID 27924948, 2016). "Downregulated gene products include putative tumor suppressor genes (SCUBE2), factors previously reported as lost in aggressive bladder cancer (FOXA1, GATA3, UPK3A), and metabolizing enzymes with polymorphisms affecting cancer risk (UGT1A10, UGT1A7)." (PMID 24134934, 2013).
bladder cancer (continued). "In the Immune-response pathway, we observed an interaction between SNPs in GATA3 and CD81, such that the combined heterozygous variant genotypes were associated with reduced bladder cancer risk." (PMID 23284679, 2012). "Interestingly, a previous study in bladder cancer stem cells showed that SUV39H1 maintains the self-renewal of these cells by repressing the transcription factor GATA3, leading to the upregulation of STAT3 and maintaining stemness." (PMID 40059829, 2025). "Interestingly, overexpression of GATA3 and FOXA1 can influence the expression of markers associated with the luminal molecular subtype of bladder cancer, suggesting potential molecular connections in UTUC." (PMID 38425344, 2024). "One research on bladder cancer found that overexpression of GATA3 and FOXA1 could influence the expression of markers associated with the luminal molecular subtype, suggesting potential molecular connections in UTUC." (PMID 38425344, 2024). "Although the suggested mechanisms reveal different aspects of bladder cancer biology and need further clarification, the results presented here provide statistically significant evidence that GATA3 in the primary biopsy is a reliable predictive factor for early relapse." (PMID 37829946, 2023). "We identified and validated GATA3 as a positive regulator of PPARG in bladder cancer." (PMID 37250326, 2023). "In bladder cancers, where GATA3 and FOXA1 may have characteristic altered gene expression, Hi-C has been used elegantly to detect patterns of CNV and SV." (PMID 35902807, 2022). "GATA3 is a key player in antitumor immunology, and continuous studies show that it might be a key biomarker for bladder cancer (BLCA)." (PMID 35647011, 2022). "LINC00885 has been proven to correlate with GATA3 in bladder cancer." (PMID 35012615, 2022). "Although GATA3 is highly expressed in bladder cancer, its high expression may adversely inhibit the progression of tumor cells in BLCA." (PMID 35647011, 2022). "Considering that high mitotic activity may predict a greater chance of tumor recurrence in human UC and, consequently, more aggressive tumor behavior, this result suggests that higher GATA-3 positivity can indicate a worse prognosis for bladder cancer in dogs." (PMID 36299636, 2022). "Previous study has proven that LINC00885 was related to GATA3 expression in bladder cancer." (PMID 35012615, 2022). "Such an imbalance between the over-expression profile of GATA3 in BLCA cancer tissues and the inhibitory function of GATA3 on bladder cancer cells may be explained by the ability of GATA3 to transform basal bladder cancer cells into luminal cells." (PMID 35647011, 2022). "Several clinical studies of GATA3 in bladder cancer have been conducted." (PMID 34707176, 2021). "Considering that it has previously been shown that bladder cancer cell lines have functional ERs, this suggests that ERα could be activated in less differentiated cells and independently of GATA3." (PMID 34690921, 2021). "GATA3 and ER have been functionally linked in the establishment of luminal fate in breast tissue, but to date their relationship in bladder cancer has not been established." (PMID 34690921, 2021). "Their results indicated that GATA3 expression showed a high association with the luminal subtype only in bladder cancers without neuro-urological history." (PMID 33910625, 2021). "While FOXA1 and GATA3 are known to have low expression in basal bladder cancer cell lines and tumors, the enrichment of forkhead and GATA motifs in open chromatins across BLCA cell lines suggests compensation by Forkhead and GATA factors other than FOXA1 and GATA3." (PMID 33858483, 2021).